RBM38 (RNA binding motif protein 38)
Diseases named in the same sentence as RBM38 in open-access papers (continued):
Sharing a sentence is not in itself a finding about the gene and the disease.
melanoma (1 paper, 2022). A malignant, usually aggressive tumor composed of atypical, neoplastic melanocytes. "In this research, we evaluated the role of RBM38 in malignant melanoma and formulated an RBM38-associated immune prognostic model (RAIPM) that can estimate the prognosis for melanoma patients." (PMID 35326741, 2022). "We found that RBM38, as an oncogene, promotes the proliferation, invasion, and migration of melanoma cells and is associated with immune infiltration and pathways." (PMID 35326741, 2022). "Melanoma patients with low-expression RBM38 were linked to better prognosis in the TCGA and GSE22155 datasets." (PMID 35326741, 2022). "Furthermore, RNA-seq analysis was used to determine the DEGs related to RBM38 and the RBM38-associated immune signature was established to predict melanoma risk." (PMID 35326741, 2022). "The results showed that RBM38 was identified as an independent factor for poor OS in patients with malignant melanoma (HR = 1.221, p = 0.029)." (PMID 35326741, 2022). "It was subsequently confirmed that RBM38 plays a role in promoting the proliferation, invasion, and migration of malignant melanoma cells in vitro and the growth of human xenograft tumors in nude mice." (PMID 35326741, 2022). "Meanwhile, RT-qPCR analysis of RBM38 mRNA expression indicated that RBM38 level was higher in 13 paired melanoma tissues than matched normal tissues." (PMID 35326741, 2022). "Meanwhile, experiments in vivo and in vitro were performed to investigate the role of RBM38 in melanoma." (PMID 35326741, 2022). "For the first time, aberrant expression of RBM38 was found to be closely related to the malignant progression of melanoma in vivo and in vitro." (PMID 35326741, 2022). "Our research found that melanoma patients with lower expression of RBM38 had a better prognosis in the TCGA-SKCM and GSE22155 datasets." (PMID 35326741, 2022). "The purpose of this study was to explore the immune response mechanism of RNA binding protein RBM38 in the development of melanoma with the screening of effective immunodiagnostic models and targeted therapy." (PMID 35326741, 2022). "Furthermore, IHC analysis provided further evidence that RBM38 protein expression level was higher in melanoma samples than normal tissue (n = 20 in each group)." (PMID 35326741, 2022). "Secondly, more melanoma cell lines could be conducted to investigate the role of RBM38 in melanoma in vivo and in vitro." (PMID 35326741, 2022). "Therefore, this research aimed to investigate the function of RBM38 in melanoma and the prognosis of the disease." (PMID 35326741, 2022). "Our results indicated that RBM38 might act as an oncogene in the progression of melanoma." (PMID 35326741, 2022). "The expression and biological function of RBM38 in malignant melanoma has not been analyzed, and it might provide a relevant diagnostic and therapeutic tool in malignant melanoma." (PMID 35326741, 2022). "Consequently, the “amplification” alteration may be relevant to the function of RBM38 in melanoma." (PMID 35326741, 2022).
pancreatic cancer (1 paper, 2026). "It represents a potential candidate gene linked to the susceptibility of type 2 diabetes, and decreased RBM38 expression can enhance the proliferation of pancreatic cancer cells in humans." (PMID 40796306, 2026).
skin cutaneous melanoma (1 paper, 2022). "RBM38 was overexpressed in 19 types of cancer samples, including skin cutaneous melanoma (SKCM)." (PMID 35326741, 2022).
squamous cell carcinoma (1 paper, 2020). A carcinoma arising from squamous epithelial cells. "Subsequently, it was shown that S385 DNp63a phosphorylation is induced by cisplatin in squamous cell carcinoma cells, leading to RNA splicing and ACIN1-mediated cell death via interaction with spliceosome components SAP18, RBM38, ELAVL, SRPK2, SRSF2, and ACIN1." (PMID 33375680, 2020).
tumor (31 papers, 2014 to 2024). "By searching the literature, we found that the RBM38’s role in the development of PC has been reported, and RBM47 and RBMS3 were closely associated with tumor immunity." (PMID 39741300, 2024). "RBM38 overexpression improved sorafenib sensitivity in ectopic transplanted tumors and suppressed the growth rate of tumor cells." (PMID 37296859, 2023). "Our findings that CALML3-AS1 serves as a tumor suppressor for PTC via sponging miR-20a-5p/RBM38 axis which would guide new therapy development in PTC treatment." (PMID 35351042, 2022). "We assessed the differences in RBM38 expression between normal tissue and tumor samples of 27 cancers with the TCGA and GTEx datasets." (PMID 35326741, 2022). "It is worth mentioning that the expression levels of RBM38 are different in different tumor, indicating that the function of RBM38 in tumors is complex." (PMID 35985767, 2022). "First, it is possible that RBM38 and p73 regulate two divergent pathways involved in chronic inflammation vs. tumor suppression." (PMID 34204113, 2021). "As chronic inflammation is closely related to cancer development, we postulate that RBM38 cooperates with p73 to regulate chronic inflammation and tumor suppression." (PMID 34204113, 2021). "Together, these data suggest that SPRR2A/2D are regulated by the RBM38-p73 axis and contributes to p73-mediate tumor suppression and inflammatory response." (PMID 34204113, 2021). "Another enigma is the significance of Rbm24 and Rbm38 in preventing p63-mediated tumor suppression because they have been shown to destabilize p63 mRNA in overexpression experiments." (PMID 32806768, 2020). "The precise regulatory mechanism of RBM38 in GC needs to be further studied to investigate its potential role and relevance in GC and to implement it as a tumor therapeutic target in GC individual therapy." (PMID 32294703, 2020). "In breast cancer, we found RBM38 acted as a tumor suppressor by regulating the mRNAs stability of PTEN and c-Myc19–21." (PMID 33145401, 2020). "Of interest, Rbm38 serves as a tumor suppressor gene, and mice that lack Rbm38 are prone to cancer development." (PMID 30087616, 2018). "It implied that RBM38-mediated increase in PTEN expression play a role in the RBM38-mediated tumor suppression process." (PMID 29052531, 2017). "In addition, effects of CREB3 on RBM38 was verified by IHC staining in mice tumor slices with CREB3 overexpression or knockdown." (PMID 38952575, 2024). "RBM38 is reported to be a tumor suppressor in HCC development." (PMID 38952575, 2024).
tumor (continued). "Finally, we constructed a model using four genes, RBMS1, ZC3HAV1, QKI, and RBM38, to calculate the Tumor Immune Dysfunction and Exclusion (TIDE) score." (PMID 37628671, 2023). "In summary, CALML3-AS1 acts as a ceRNA to inhibit tumor progression via miR-20a-5p/RBM38 axis." (PMID 35351042, 2022). "Thus, RBM38 can also function as a tumor repressor or as an oncogene, depending on the cancer types." (PMID 35406615, 2022). "Moreover, the IHC analysis showed that the protein level of RBM38 was higher in human tumor tissues than in normal tissues." (PMID 35326741, 2022). "In addition, IHC analysis confirmed the higher RBM38 expression in tumor tissues than normal tissues." (PMID 35326741, 2022). "To this end, we identified small proline-rich protein 2A and 2D (SPRR2A and SPRR2D) as novel targets of p73, which may contribute to inflammation and tumor suppression regulated by the RBM38-p73 axis." (PMID 34204113, 2021). "Together, we concluded RBM38 acted as a tumor suppressor partially by enhancing PTEN expression." (PMID 29052531, 2017). "Moreover, in vivo tumor formation experiments showed that knockdown of RBM38 expression significantly inhibited melanoma cancer cell growth, and overexpression of RBM38 expression significantly increased melanoma cancer cell growth in nude mice." (PMID 35326741, 2022). "Recent studies revealed that aberrant expression of RBM38 was related to high malignancy and worse OS in various cancers, and its target genes were involved in regulating the process that results in malignant phenotypes such as tumor cell proliferation, invasion, and metastasis." (PMID 35326741, 2022). "Thus, chronic systemic inflammation observed in Rbm38−/−;Trp73+/− mice may be responsible for early death and shortened lifespan, which precedes tumor development." (PMID 34204113, 2021). "Thus, further studies are warranted to determine whether SPRR2A/2D expression mediated by the RBM38-p73 axis links chronic inflammation and tumor suppression." (PMID 34204113, 2021). "But recently, more and more studies suggested that RBM38 might act as a tumor suppressor." (PMID 30662454, 2018). "Thus, further studies are needed to address the functional link between RBM38 and HIF1α under the hypoxic tumor microenvironment, which may explain how tumors thrive under a hypoxic condition." (PMID 25622105, 2015). "It was shown that some members of the RBM proteins family play a tumor-suppressive role in cancers, inhibiting tumorigenesis and cell proliferation, promoting tumor cell apoptosis, and limiting cell migration and invasion, such as RBM6 and RBM38." (PMID 34804951, 2021). "It was previously found that two other RBMs, RBM38 and RBMS2 acted as tumor suppressor in breast cancers." (PMID 33145401, 2020). "In conclusion, CREB3 acted as a tumor suppressor in HCC, which inhibited AKT phosphorylation through independently interfering interaction of INSR with IRS1, and transcriptionally activating RBM38." (PMID 38952575, 2024).
tumor (continued). "Statistical analyses indicted that the tumor incidence for Rbm24+/− mice was not significantly different from that for WT mice (p = 1.0 by Fisher’s exact test), but less than Rbm38−/− mice (p = 0.0227 by Fisher’s exact test)." (PMID 36478739, 2022). "In addition, the expression level of EEF1D, RBM38 and WDR43 ascended with higher tumor pathology grade (p-value = 0.019, 0.020, 0.034)." (PMID 34863153, 2021). "Despite the fact that chronic inflammation is closely related to cancer development, we did not observe enhanced tumor penetrance in Rbm38−/−;Trp73+/− mice." (PMID 34204113, 2021). "Similarly, while Trp73+/− or Rbm38−/− mice developed more numerous spontaneous tumors than Rbm38−/−;Trp73+/− mice, the rate of tumor incidence between Rbm38−/−;Trp73+/− and Trp73+/− or Rbm38−/− mice was not statistically significant." (PMID 34204113, 2021). "Moreover, hsa-miR-532-5p, RBM38, EGLN1, and DLEU1 were demonstrated as both oncogenes and tumor-suppressors in non-CESC cancers and their roles in CESC were unclear." (PMID 30662454, 2018). "However, no study was performed to investigate the possible roles of RBM38 in CESC, and our analysis prompted to assume that RBM38 may be a tumor suppressor in CESC." (PMID 30662454, 2018).
cancer (24 papers, 2012 to 2026). A tumor composed of atypical neoplastic, often pleomorphic cells that invade other tissues. "The RNA-binding motif protein 38 (RBM38) is a member of the RNA recognition motif family of RBPs; the gene which encodes RBM38 is located on chromosome 20q13, and is downregulated in various cancer tissues." (PMID 37296859, 2023). "Interestingly, previous studies showed that Rbm38 is frequently altered in various types of cancers and Rbm38-deficient mice were prone to spontaneous tumors." (PMID 36478739, 2022). "It is also important to understand how the expression and activity of Rbm24 or Rbm38 are dysregulated in cancer cells." (PMID 32806768, 2020). "A further understanding of the functional consequences of Rbm24 and Rbm38 in regulating cancer-related gene expression should help to define novel therapeutic strategies for modulation of their activity." (PMID 32806768, 2020). "These works identify a critical role of the eIF4E-binding motif to modulate RBM24/RBM38 activity in cancer cells and raise the possibility that disrupting RBM24/RBM38-eIF4E complex may represent a potential therapeutic approach for cancer treatment." (PMID 35406615, 2022). "Therefore, we further verified the molecular mechanism of CALML3-AS1 through miR-20a-5p and RBM38 on cancer regulation." (PMID 35351042, 2022). "Interestingly, some genes of the amplicon for which data are available in the human protein atlas, such as PCK1, PMEPA1, and RBM38, are expressed in the protein level at low to moderate levels in several cancers." (PMID 30275357, 2018). "RBM38 is found to be overexpressed in several types of cancers." (PMID 25622105, 2015). "The precise mechanism may be associated with the role of RBM38 and GAS5 in EGFR activation, c-Jun activation, autophagy, protein kinase B activation, formation of a hypoxic environment, dysregulation of apoptosis, cancer stem cell renewal, and epithelial–mesenchymal transition." (PMID 37296859, 2023). "The expression level of EEF1D, RBM38 and WDR43 ascended with the progression of cancer pathology grade." (PMID 34863153, 2021). "Additional targets of HOTAIR, identified in HepG2, Bel-7402 and Huh7 cells, include RNA binding motif protein 38 (RBM38), miR-145, and miR-122, promoting cancer phenotypes." (PMID 32429062, 2020). "However, at least in several cancer cell lines, phosphorylation of the serine residue by glycogen synthase kinase 3 (GSK3) prevents the interaction with eIF4E and converts Rbm24 or Rbm38 into an activator of mRNA translation." (PMID 32806768, 2020).
infection (1 paper, 2019). The state of being infected such as from the introduction of a foreign agent such as serum, vaccine, antigenic substance or organism. "In addition, RBM38 may regulate LTNPs through the stability of CDKN1A and the down-regulation of MS4A6A may modify infection of HIV-1 in LTNPs." (PMID 30626383, 2019).
inflammation (1 paper, 2021). Aberrant reaction of the microcirculation characterized by movement of fluid and leukocytes from the blood into extravascular tissues. "Since Trp73+/− and Rbm38−/− mice were prone to chronic systemic inflammation, that is, chronic inflammation in three or more organs, we sought to determine whether compound Rbm38−/−;Trp73+/− mice are also susceptible to chronic systemic inflammation." (PMID 34204113, 2021).
RBM38 also shares sentences with these, for which no sentence is quoted: ovarian carcinoma (4 papers); breast tumor (3); acute myeloid leukemia (2); chronic lymphocytic leukemia (2); papillary thyroid cancer (2); adenoma (1); bladder cancer (1); depression (1); esophageal adenocarcinoma (1); esophageal cancer (1); gastric cancer (1); glioblastoma (1); glioma (1); lung adenocarcinoma (1); lymph node metastasis (1); neuroblastoma (1); osteosarcoma (1); prostate carcinoma (1); psychiatric disorder (1); renal carcinoma (1); renal cell carcinoma (1); type 2 diabetes (1).